CTSK (cathepsin K)
Diseases named in the same sentence as CTSK in open-access papers (continued):
Sharing a sentence is not in itself a finding about the gene and the disease.
ovarian tumors (1 paper, 2018). "To further validate their possible contribution to OC mesenchymal subtype, we found that both CXCR7 and CXCL11 strongly correlate with genes associated with ECM and OC invasion, such as PRRX1, TMEM45A, and CTSK, when analyzed in the mesenchymal counterpart of ovarian tumors." (PMID 30051594, 2018).
Peri-Implantitis (1 paper, 2025). An inflammatory process with loss of supporting bone in the tissues surrounding functioning DENTAL IMPLANTS. "NFATc1 serves as a crucial regulator of osteoclast differentiation and is involved in regulating the activity of osteoclastic genes such as thrombin receptor activator protein and cathepsin K.33These findings demonstrate the capacity of hUCMSCs in preventing bone resorption in peri-implantitis." (PMID 39510521, 2025).
pituitary adenomas (1 paper, 2022). "This retrospective cohort study aimed to study the expression of tumoral biomarkers (CTSK, MMP9, MMP2, TIMP2, and PTTG1) and evaluate their clinical significance in non-functioning pituitary adenomas (NFPAs) with different invasion patterns." (PMID 36052250, 2022).
pituitary apoplexy (1 paper, 2022). A rare, potentially life-threatening disorder caused by acute ischemic infarction or hemorrhage in the pituitary gland. "No evident correlation was found between expression levels of CTSK and other clinical features of PAs, including gender, age, pituitary apoplexy, and tumor texture." (PMID 36052250, 2022).
pneumoconiosis (1 paper, 2024). An occupational lung disorder caused by inhalation of dust particles. "Although POLCs were rare in the single-cell dataset, TRAP+CTSK+ cells are abundant in the lung tissue sections from patients with coal workers pneumoconiosis (CWP; figs." (PMID 38985878, 2024).
renal angiomyolipoma (1 paper, 2021). "Among the genes upregulated in the TSC2−/− organoids were: MLANA, PMEL, GPNMB, CTSK, and ACTA2, with median expression fold change 121x-, 88x-, 34x-, 14x-, 9.5x, respectively, all of which are known to be highly expressed in the renal angiomyolipoma." (PMID 34764250, 2021).
salivary gland carcinoma (1 paper, 2023). A carcinoma that arises from the major or minor salivary glands. "Although there are several mechanisms of tumor growth, metastasis, and cancer cell invasion related to CTSK, its expression in primary tumors including salivary gland carcinomas has not been thoroughly investigated." (PMID 37198626, 2023).
salivary gland tumors (1 paper, 2023). "Best to our Knowledge, our study is the first study that present the role of CTSK in malignant salivary gland tumors." (PMID 37198626, 2023). "In the literature review, little information was present about the role of CTSK in salivary gland tumors." (PMID 37198626, 2023).
sarcopenia (1 paper, 2025). Progressive decline in muscle mass due to aging which results in decreased functional capacity of muscles. "This study explores the relationship between circulating cathepsin K (CatK) and cathepsin D (CatD) levels and sarcopenia in older adults." (PMID 41001380, 2025).
seminoma (1 paper, 2023). A radiosensitive malignant germ cell tumor found in the testis (especially undescended), and extragonadal sites (anterior mediastinum and pineal gland). "To further examine the functions of MMP9 and CTSK in seminoma, we subset immune cells (PTPRC+), and explored the expression patterns of markers for T cells (CD3D+ and CD3E+) and B cells (CD79B+; MS4A1+ and SDC1+)." (PMID 38123589, 2023). "Moreover, our work reveals spatial heterogeneity in the distribution of T cells with different functional states in tumors, while macrophages in seminoma can participate in extracellular matrix degradation through the secretion of MMP9 and CTSK." (PMID 38123589, 2023).
Sepsis (1 paper, 2025). Sepsis is defined as life-threatening organ dysfunction caused by a dysregulated host response to infection. "Sepsis-induced cleavage of Angiopoietin-2 converted it from a Tie2 agonist to an antagonist through cathepsin K-mediated proteolysis." (PMID 40029709, 2025). "Inhibiting cathepsin K with odanacatib improved survival in sepsis, highlighting its potential as a therapeutic target." (PMID 40029709, 2025). "Cathepsin K inhibition with the phase 3 small-molecule inhibitor odanacatib improved survival in distinct murine sepsis models." (PMID 40029709, 2025).
skin carcinoma (1 paper, 2013). "Cathepsin K, a lysosomal cysteine protease, is expressed in the tumor microenvironment (TME) of skin carcinoma, but nothing is known about cathepsin K in oral tongue squamous cell carcinoma (OTSCC)." (PMID 23951042, 2013).
skin squamous cell carcinoma (1 paper, 2013). A carcinoma arising from the squamous cells of the epidermis. "However, in skin squamous cell carcinomas, epithelial expression of cathepsin K was reported absent or focal and weak compared with the TME." (PMID 23951042, 2013).
systemic lupus erythematosus (1 paper, 2024). An autoimmune multi-organ disease typically associated with vasculopathy and autoantibody production. "CTSK also contributes to the pathogenesis of systemic lupus erythematosus (SLE), one of the top pathways identified in the bioinformatic analyses." (PMID 38624208, 2024).
thrombosis (1 paper, 2024). "Here, we explored the role(s) of CTSK in the pathogenesis of chronic stress-related thrombosis in mice subjected to chronic restraint stress conditions." (PMID 38703204, 2024).
thyroid cancer (1 paper, 2024). "This study demonstrates that CTSK is linked to poor prognosis in thyroid cancer (THCA) and actively promotes the proliferation and migration of THCA cells." (PMID 39559351, 2024).
triple-negative breast carcinoma (1 paper, 2019). An invasive breast carcinoma which is negative for expression of estrogen receptor (ER), progesterone receptor (PR), and human epidermal growth factor receptor 2 (HER2). "Importantly, follow-up analysis by real-time PCR confirmed that a number of genes associated with osteomimicry (CTSK, SPP1 and RANK) were upregulated in ER+ and triple-negative breast cancer cell lines and PDXs that had metastasised to bone, compared with their associated primary tumours." (PMID 31783893, 2019).
Ureteral obstruction (1 paper, 2020). Obstruction of the flow of urine through the ureter. "Interestingly, using a model of unilateral ureteral obstruction, the authors found that CTSB or CTSL deficiency in mice exacerbates kidney fibrosis, whereas CTSS or CTSK deficiency protects it." (PMID 33379277, 2020).
Ventricular arrhythmia (1 paper, 2022). "In Human Phenotype Ontology, CTSK, GGCX and KCNH2, have been linked to bone-related conditions, coagulation defects and ventricular arrhythmia respectively." (PMID 35246263, 2022).
tumor (131 papers, 2008 to 2026). "Research has demonstrated that cathepsin K (CTSK), produced following dysbiosis of the gut flora, stimulates M2 tumor-associated macrophages (TAMs) to secrete IL-17, subsequently activating the NF-kB pathway and facilitating CRC invasion and metastasis." (PMID 39906741, 2024). "In human colorectal cancer tissues, the overexpression of cathepsin K is consistently associated with increased M2 tumor-associated macrophages (TAMs) in the stroma, which is related to tumor metastasis and poor prognosis." (PMID 39148909, 2024). "Multiple Cox regression demonstrated that higher CTSK expression (P=0.011), subtotal resection (P<0.001), invasion (P=0.037), and larger tumor diameter (P=0.001) were independent risk factors for recurrence." (PMID 36052250, 2022). "Expression of CTSK was related to high concentration of M2 tumor-associated macrophages (TAMs) M2 in CRPC." (PMID 36138018, 2022). "As we know, TLR4 recognizes cathepsin K to activate the M2 polarization of tumor-associated macrophages (TAMs) through an mTOR-dependent pathway, resulting in tumor metastasis." (PMID 36204682, 2022). "The presence of cathepsin K in the sera of PCa patients has been associated with tumour aggressiveness and is regarded as a contribution to bone resorption." (PMID 36428597, 2022). "Similar to the dysregulated Cathepsin B expression in the tumor microenvironment inducing tumor progression, Cathepsin K over-expression is associated with cancer metastatic disease, indicating its potential diagnostic and prognostic value." (PMID 32927648, 2020). "Over the past few years, accumulated data have shown overexpression of Cathepsin K in multiple cancer types, indicating its role in tumor progression and its potential diagnostic and prognostic values." (PMID 32927648, 2020). "The importance of a clearer mechanistic understanding of cathepsin K secretion is underscored by the ongoing development and trials of a cathepsin K inhibitor (odanacatib) to prevent bone loss and tumor metastasis to bone." (PMID 25992615, 2015). "Our findings suggested that CTSK has the potential to facilitate the initiation and progression of GC by augmenting the invasive capacity of GC cells, engaging in tumor-associated EMT, and fostering the establishment of an immunosuppressive tumor microenvironment (TME)." (PMID 38856944, 2024). "Wang and his coworkers reported elevated CTSK levels at tumor-associated macrophages in NSCLC." (PMID 37198626, 2023). "CTSK encoding cathepsin K, a lysosomal cysteine proteinase that could contribute to tumor invasiveness, was also decreased." (PMID 37834191, 2023). "Such as M2 macrophages cells, resting mast cells, monocytes cells, and negatively related to M1 macrophages cells, suggesting that the CTSK level was closely related to TAM.TAM as an important part of TME is an important regulators of tumor-associated inflammation." (PMID 37930479, 2023). "Finally, the influence of CTSK and IL-17A on tumor-associated macrophages M2 in PC tissues was verified by database analysis and appropriate experiments." (PMID 36138018, 2022). "Previously, cathepsin K expression in cancer was thought to be limited to osteoclasts, having distinct but synergistic effects on matrix metalloproteases (MMPs) in bone resorption associated with tumor metastasis." (PMID 23951042, 2013). "Interestingly, CTSK is a known biomarker for a variety of cancer types and its expression is associated with metastasis of human solid malignancies suggesting a broader functional role for CTSK in human tumor metastasis." (PMID 36738455, 2023). "In addition, cathepsin K is closely related to cancer, specifically in processes associated with tumor growth, metastasis, and cancer cell invasion, as well as their interactions with the tumor microenvironment." (PMID 34069976, 2021).
tumor (continued). "Positive TRAP staining was observed at the bone-tumour interface in addition to Cathepsin K positive cells in a serial histological section, confirming HN bone resorption and remodelling occurred in an osteoclast-mediated process." (PMID 41315643, 2025). "Tartrate-resistant acid phosphatase (TRAP) staining and Cathepsin K IHC were then performed to determine the presence and activity of osteoclasts within the OS tumour microenvironment." (PMID 41315643, 2025). "This polarization stimulates tumor cells to produce enzymes like cathepsin K, promoting tumor growth." (PMID 39273009, 2024). "This acidic environment upregulates matrix MMPs, and BMAs further contribute to bone matrix degradation by upregulating expression of OC-specific genes such as cathepsin K, facilitating tumor cell growth." (PMID 38571500, 2024). "A recent study proposed that cathepsin K secreted by tumor cells binds to TLR4, leading to the M2 polarization of TAMs through an mTOR-dependent mechanism." (PMID 39148909, 2024). "Patient 2, who was diagnosed with recurrent ACP after primary tumour resection, showed the highest expression levels of CTSK and MMP-9." (PMID 38594611, 2024). "Since it includes genes such as CHOP, CTSK and SAT1, SFI was associated with the tumor cell apoptosis pathway and ferroptosis pathway." (PMID 38809316, 2024). "Tumor-enriched macrophages (CTSK+ and C1QC+ macrophage) and WNT5A+ inflammatory fibroblast states, which contribute to diverse aspects of tumorigenesis, were also found in the pro-tumorigenic community." (PMID 38744958, 2024). "CTSK promoted the tumor growth and metastasis by IL-17/CTSK/EMT axis and mediates M2 macrophage polarization in CRPC." (PMID 38887275, 2024). "We already described the tumor promoting effect of cathepsin K, and of lysine demethylase Kdm2a in LC which stimulates Erk1/Erk2 signaling through epigenetic silencing of DUSP3." (PMID 38245882, 2024). "CTSK promotes the tumor growth and metastasis by IL-17/CTSK/EMT axis and mediates M2 macrophage polarization in CRPC." (PMID 38887275, 2024). "The levels of the tumor-secreted cytokine CTSK in the supernatant of OSCC cells were further measured by ELISA assay." (PMID 38993570, 2024). "Immunohistochemistry showed that the tumor cells were strongly positive for cathepsin-K, HMB45 and TFE3." (PMID 36647137, 2023). "The present work found CTSK as a potential predictive biomarker and immunotherapeutic target for GC based on the tumor microenvironment (TME)." (PMID 37930479, 2023). "Next, a series of methods and tools were employed to explore the relationships between clinicopathological features of GC and CTSK expression as well as prognosis, tumor immune microenvironment, immune checkpoints and drug sensitivity." (PMID 37930479, 2023). "Today, high CTSK expression has been reported in several neoplasms of epithelial and mesenchymal origin." (PMID 37198626, 2023). "Cathepsin K (encoded by CTSK), a lysosomal cysteine proteinase involved in bone remodeling and tumor invasiveness, is known to cleave and activate MMP9 in tumors." (PMID 38123589, 2023). "CTSK has a principal role in cancer invasion and progression through interaction with the tumor microenvironment, degradation of extracellular membrane proteins, and destruction of the elastic lamina of blood vessels." (PMID 37198626, 2023). "Recent studies have shown that an imbalance in the gut microbiota can upregulate the expression of histone-degrading enzyme cathepsin K (CTSK), which is secreted by tumor cells and has been linked to tumor metastasis." (PMID 37943609, 2023). "TAM in TME can be polarized into both M1 (anti-tumor) and M2 (pro-tumor) phenotypes, while CTSK expression level was positively correlated with M2 macrophages and can drive M2 polarization of TAM." (PMID 37930479, 2023). "Firstly, the experimental data lacked more detailed clinical information, pointing to a gap between CTSK and more detailed clinicopathological features of tumor patients." (PMID 37930479, 2023).
tumor (continued). "Cathepsin K (CTSK) is a protease that degrades type I collagen and extracellular matrix, thereby contributing to bone resorption and tumor invasion." (PMID 36052250, 2022). "This study found that tumor-derived exosomes not only promote tumor invasion and metastasis but also inhibit osteoclast differentiation, and CTSK expression is downregulated." (PMID 36005209, 2022). "During bone resorption, CTSK-positive cells accumulate at the tumor–bone interface until the bone is destroyed." (PMID 36005209, 2022). "In this cluster, the expression of many AML tumor marker genes was unaffected by rapamycin, in contrast to other clusters where rapamycin suppressed the expression of these tumor genes, including CTSK." (PMID 36028490, 2022). "Previous studies had reported that CTSK shows high expression in tumor cells that are highly invasive." (PMID 36138018, 2022). "Results demonstrated that low expression of CTSK in localized PC is accompanied by low collection of M2 TAMs in stroma of the tumor." (PMID 36138018, 2022). "Previous studies have demonstrated that the inhibition of CTSK can significantly decreased the phosphorylation of mTOR at S2448 in Caki cells and reduced tumor growth and induced cell death in a xenograft model." (PMID 36005209, 2022). "And the tumor weight/volume of CTSK siRNA group of mice were the smallest when compared with the rest of three groups." (PMID 36138018, 2022). "Expression of β-catenin and vimentin was found to be higher in the tumor regions of mice with high CTSK expression while the expression of E-cadherin was low." (PMID 36138018, 2022). "Overall, cathepsin K is helpful for recognizing these types of tumor entities and distinguishing them from other eosinophilic renal tumors most frequently encountered in daily clinical practice." (PMID 34069976, 2021). "In one case of a particularly aggressive tumor, the growing mass passed through the bone of sellar floor to invade the sphenoid sinus in a cathepsin K-dependent manner." (PMID 34970226, 2021). "This is consistent with the conclusion that Cathepsin K is highly expressed during tumor invasion and metastasis and has a stimulating effect on the aggressive phenotype of various types of cancer." (PMID 32927648, 2020). "CTSK overexpression has been detected in breast, prostate, and gastrointestinal cancers, and correlated with tumor stroma." (PMID 32695142, 2020). "Lower CTX-I serum level, a decreased number of TRAP+ osteoclasts and lower Cathepsin-K expression observed at the tumor-bone interface indicated that osteoclastogenesis was inhibited in RiCKO mice." (PMID 31595162, 2019). "In univariate analysis, high CTSK expression (tumor and stroma) appeared to be an important independent predictive factor of lymph node involvement (tumor: OR = 7.65, CI: 2.51–23.32; p < 0.001 and stroma: OR = 4.04, CI: 1.57–10.36; p = 0.004)." (PMID 29618339, 2018). "The biological role of CTSK in promoting tumor invasion and migration has been proved ex vivo in cell-based systems." (PMID 29618339, 2018). "In contrast, there was a significant association with histopathologically proven LNM (p < 0.01) and increased CTSK expression in both tumor and stromal cells." (PMID 29618339, 2018). "CTSK Protein expression was semi-quantitatively determined by immunohistochemistry in tumor and stromal cells." (PMID 29618339, 2018). "A total of 213 (64%) cores with tumor and 246 (74%) cores with stroma stained with the CTSK antibody were available for analysis." (PMID 29618339, 2018). "A similar strong relationship to peri-neural invasion was also demonstrated (p = 0.01) for CTSK tumor cell expression." (PMID 29618339, 2018). "Logistic regression analysis highlighted increased CTSK protein expression in tumor cells as the most significant independent factor of lymphatic metastasis (OR = 7.65, CI:2.31–23.31, p = 0.001)." (PMID 29618339, 2018).